EPO (erythropoietin)
Diseases named in the same sentence as EPO in open-access papers (continued):
Sharing a sentence is not in itself a finding about the gene and the disease.
Hypertension (154 papers, 2005 to 2026). The presence of chronic increased pressure in the systemic arterial system. "While polycythaemia is a recognised risk factor for hypertension (e.g., Gaisböck syndrome), erythropoietin has been shown to cause hypertension independently from elevated hematocrit." (PMID 39653728, 2025). "It is well known that treatment with EPO increases blood pressure and the risk of hypertension, but the mechanism is unclear." (PMID 41155680, 2025). "The missense variant of rs723580 was reported to be a top trans-eSNP for the expression level of EPO associated with the red blood cell traits that were strongly linked to hypertension." (PMID 37936055, 2023). "Angiotensin II helps in the erythropoietin-mediated proliferation of red cell precursors which in turn raises the hematocrit and causes hypertension." (PMID 36830925, 2023). "Another well-known cause of hypertension in haemodialysis patients is erythropoietin-stimulating agents (ESA)." (PMID 37773103, 2023). "In this group of patients, anemia of these patients at high altitude seems to be corrected with lower doses of erythropoietin compared to patients at sea level but they have higher risk of hypertension and thrombotic events." (PMID 37675017, 2022). "Phlebotomy has demonstrated to be useful for the sustained management of erythropoietin (EPO)-induced malignant hypertension in patients on chronic hemodialysis and post-transplant hypertension associated with erythrocytosis." (PMID 34764381, 2021). "We mainly studied clinical trials that unraveled the mechanism of hypertension caused by erythropoietin." (PMID 33628672, 2021). "Risk factors for intradialysis hypertension were males, frequent erythropoietin use while for intradialysis hypotension, were female gender and less frequent dialysis." (PMID 38322382, 2021). "Since erythropoietin therapy is well known to cause hypertension, the patients receiving erythropoietin must be monitored for their blood pressure changes." (PMID 33628672, 2021). "Nevertheless, hematopoietic effects of repeated EPO administration are associated with increased risk of hypertension and blood clotting." (PMID 29673379, 2018). "Administration of EPO inevitably induces elevation of hematocrit levels (Ht), which can cause undesirable side effects such as arterial hypertension and thromboembolism." (PMID 28288167, 2017). "The risk factors of hypertension development comprise also an acquired cause of CKD, hypertension before dialysis, poor dialysis efficacy, erythropoietin administration, shorter dialysis duration and lower mean hemoglobin and calcium levels." (PMID 27882810, 2017). "If erythropoietin agents are used they should only be used in low doses because of the dangers of thromboembolic phenomena and hypertension associated with high doses of ESA." (PMID 26096008, 2015). "Another frequently used medication in HD patients associated with hypertension is erythropoietin (EPO)." (PMID 24967230, 2013). "However, its use at high doses, in some cases, is associated with hypertension and thrombosis, as a result, erythropoietin treatment should be carefully monitored." (PMID 39881295, 2025). "Although volume overload and sodium retention appear to be the main pathogenic mechanisms of hypertension in this population, other factors, such as oxidative stress, the use of recombinant erythropoietin, and the uncoupling of eNOS, may also be involved." (PMID 38540300, 2024). "For example, erythropoietin may cause adverse effects such as hypertension and thrombosis, whereas long-term use of iron may lead to gastrointestinal discomfort or excessive accumulation." (PMID 39845803, 2024). "The incidence rate of EPO-associated hypertension is estimated to be 10–15%." (PMID 38029231, 2023).
Hypertension (continued). "The increase of RDW reflects the abnormality of RBC production, metabolism, and survival, caused by abnormal erythropoietin function, hypertension, oxidative stress, poor nutritional status, dyslipidemia, inflammation, RBC fragmentation, and shortened telomere length." (PMID 37908808, 2023). "Hypertension, diabetes, the deficiency of vitamin D and erythropoietin, proteinuria, high concentrations of fibroblast growth factor 23 (FGF-23), elevated uremic toxins and also the accumulation of advanced glycation end-products (AGEs) are the causes of endothelial dysfunction in CKD." (PMID 36364925, 2022). "EPO causes hypertension in normal subjects, dialysis, and predialysis patients." (PMID 33628672, 2021). "Antinatriuresis can be the cause of EPO-induced hypertension." (PMID 33628672, 2021). "Thus, it indicates that angiotensin is an important factor mediating the hypertensive effect of erythropoietin and polymorphism of the angiotensinogen gene has a bearing on the development of hypertension." (PMID 33628672, 2021). "Individuals homozygous for particular allele are at greater risk of EPO-induced hypertension." (PMID 33628672, 2021). "Angiostensinogen gene polymorphism is associated with EPO-induced hypertension." (PMID 33628672, 2021). "High hematocrit resulting from chronically administered EPO, particularly at high dose, is associated with adverse effects such as hypertension and thromboembolism and could counteract the neuroprotective and cardioprotective effects of EPO." (PMID 32038269, 2019). "Drugs used commonly as adjuvants such as steroids, erythropoietin stimulating agents etc, may also cause rise in blood pressure or exacerbate preexisiting hypertension." (PMID 29755695, 2018). "However, hematopoietic effects of repeated EPO administration are associated with risk of hypertension and blood clotting." (PMID 30400939, 2018). "Furthermore, drugs commonly administered in CKD can cause iatrogenic hypertension (e.g., erythropoietin, glicocorticosteroids, growth hormone)." (PMID 27882810, 2017). "However, safety concerns have been raised over long-term and high-dose application of EPO, which has been associated with hypertension and thrombosis." (PMID 26459940, 2015). "However, systemic EPO would expose to an undesirable increased in hematocrit associated with consequences such as increased risk of hypertension, thrombosis or myocardial infarction." (PMID 25422898, 2014). "However, this approach presents clinical challenges and safety concerns, including hypo responsiveness to EPO, potential adverse effects such as hypertension and cardiovascular events, and the risk of iron overload, which warrants an in-depth study on novel drugs like HIF-PHI." (PMID 38021836, 2023). "Besides, there was a risk due to EPO-dependent blood viscosity increase and hypertension, and Ethics Committees could have been reluctant to approve the protocol." (PMID 15910687, 2005). "Increased BP is linked to elevated erythropoietin (EPO) levels in individuals with essential hypertension due to the vasoconstrictor action of EPO." (PMID 41154669, 2025). "Nitric oxide resistance has been proposed as a contributing mechanism in EPO-induced hypertension and constant exposure to elevated glucocorticoid levels is known to cause polycythemia." (PMID 41154669, 2025). "SGLT-2i have been observed to diminish intraglomerular hypertension and hyperfiltration, reduce albuminuria, and augment erythropoietin production, thereby decelerating nephropathy progression." (PMID 39567483, 2024). "The cause of this comorbidity among HD patients is multifactorial and is linked besides arterial hypertension and fluid overload to specific CKD complication factors (vitamin D, erythropoietin, calcifications, etc.)." (PMID 38535084, 2024). "In mice, EPO increased hypertension in vivo and contractility in mouse aortic smooth muscle cells in vitro." (PMID 38628440, 2024).
Hypertension (continued). "All these agents, i.e., EPO, ESA, and PHIs, are associated with hypertension and major adverse cardiovascular events (MACEs) in the trials." (PMID 38125882, 2023). "Meanwhile, the incidence of hypertension with erythropoietin use is estimated to be approximately 10% to 15% and is associated with NO, endothelins, and the sympathoadrenal and renin-angiotensin pathways." (PMID 37919317, 2023). "The presence of hypertension and erythropoietin were more prevalent among patients with high TSH levels." (PMID 36655149, 2023). "Regarding possible absolute or relative contraindications of EPO, all patients were evaluated for a history of anaphylaxis, uncontrolled hypertension, active thromboembolism, and active seizures." (PMID 38029231, 2023). "On the other hand, by the same reasoning, these same effects of EPO have previously been blamed for the occurrence of arterial hypertension." (PMID 35847006, 2022). "Most hypertension cases take place with erythropoietin in conditions of severe renal impairment and with dialysis, while others of animals or human studies reporting the administration of erythropoietin with normal kidneys showed less advanced BP effects." (PMID 36304157, 2022). "The most frequent comorbidity, in both short- and long-acting EPO-treated groups, was arterial hypertension." (PMID 35464768, 2022). "One common side effect of erythropoietin use is hypertension, which can occur in both healthy and diseased patients taking this drug." (PMID 33628672, 2021). "It is believed that increase in hematocrit and blood viscosity after treatment with recombinant human erythropoietin alters vascular responsiveness and increases vascular resistance, which leads to hypertension." (PMID 33628672, 2021). "In this review article, we have discussed about hypertension, which develops as a result of erythropoietin therapy." (PMID 33628672, 2021). "Mechanisms of polyglobulia or EPO-induced hypertension include increased blood-viscosity and EPO-related vasoconstriction." (PMID 34764381, 2021). "In this review article, we have discussed in detail about the mechanism behind hypertension with erythropoietin use." (PMID 33628672, 2021). "We have explored the pathogenesis of erythropoietin-induced hypertension and discussed some ways to prevent and treat this condition." (PMID 33628672, 2021). "Intradialysis hypotension was commoner in females, diabetics and with less frequent dialysis while intradialysis hypertension was commoner in males, frequent erythropoietin use." (PMID 38322382, 2021). "Hypertension, thrombosis, and stroke are the well-known complications of erythropoietin, especially when it is used to achieve high hemoglobin target levels." (PMID 33628672, 2021). "We used different keywords such as erythropoietin and hypertension alone and in various combinations to look for data on two databases, namely PubMed and Google Scholar." (PMID 33628672, 2021). "Although both are at high altitude hence in a hypoxemic environment which would increase erythropoietin production, the fact that urban Puno has higher prevalence of diabetes and hypertension would explain the lower eGFR in comparison to rural Puno." (PMID 31063411, 2019). "This deregulation induced chronic inflammation, the elevation of oxidative stress, erythrocyte fragmentation, poor nutritional status, hypertension, dyslipidemia, impairment of erythropoiesis, and erythropoietin dysfunction." (PMID 31496893, 2019). "(2013) demonstrated that oxidative stress plays a role in EPO‐induced hypertension in humans, and in gluteal subcutaneous resistance arteries isolated from these patients, Tempol restored endothelial function." (PMID 29939494, 2018). "Hypertension due to increased sympathetic nerve activity has been shown in patients with hypoxia, and we think that EPO in the RVLM neurons plays an important role in these patients." (PMID 29443550, 2018).
Hypertension (continued). "Increased levels of endothelin-1 and erythropoietin have been suggested as possible factors of GC-induced hypertension." (PMID 30261581, 2018). "Hypertension, diabetes, aging and concomitant medication can also interfere with erythropoietin-mediated cardioprotection in clinical settings." (PMID 28109258, 2017). "Patients who have their dialysis during the day (morning and afternoon) have more controlled hypertension, less left ventricular hypertrophy, reduced resistance to erythropoietin treatment and better quality of life than those who undergo dialysis at night." (PMID 27045416, 2016). "Unfavorable changes in the interstitial microenvironment such as inflammation, oxidative stress and ischemia resulting from hypertension can impair the function of EPO-producing cells." (PMID 25884723, 2015). "In multivariate analyses, the associations of EPO and GFR with hepcidin remained statistically significant, even after adjustment for markers of inflammation and clinical variables, e.g. hypertension and hyperlipidemia (models 1 and 2)." (PMID 25894587, 2015). "Erythropoietin works by stimulating the bone marrow to release more reticulocytes, and is known to induce or exacerbate hypertension in ESRD patients." (PMID 24411012, 2014). "EPO levels in the amniotic fluid correlate well with the EPO levels in the cord plasma and are significantly higher in pregnancies complicated by hypertension than in normal pregnancies." (PMID 22284751, 2012). "The most frequent event observed with recombinant EPO treatment is hypertension, but headache, flu-like syndrome, rash, vascular thrombosis and others can appear." (PMID 15910687, 2005). "Some studies suggest that elevated EPO may contribute to hypertension by increasing calcium ion influx into vascular smooth muscle cells via L-type calcium channels." (PMID 40951009, 2025). "In addition to inflammation, various etiologies have been proposed in the literature, such as shortening of telomere length, oxidative stress, red cell fragmentation, dyslipidemia, malnutrition, hypertension and abnormality of erythropoietin activity." (PMID 40807003, 2025). "Abnormal RDW may be associated with metabolic abnormalities including telomere shortening, oxidative stress, inflammation, poor nutritional status, dyslipidemia, hypertension, erythrocyte fragmentation, and altered erythropoietin function." (PMID 39963106, 2025). "The systemic effects of EPO, including increased hematocrit and potential hypertension, may synergize with its direct effects on the spleen to create a unique immunological microenvironment." (PMID 40191193, 2025). "Short telomere length, inflammation, oxidative stress, poor nutritional status, erythrocyte fragmentation, dyslipidemia, hypertension, and abnormality in erythropoietin function may represent potential biological mechanisms." (PMID 38426083, 2024). "This could be explained by the relative hypoxia the fetus experiences during a pregnancy, exacerbated by hypertension, which prompts the production of erythropoietin, which in turn encourages erythropoiesis, resulting in an increase in RBC counts in neonates." (PMID 38183053, 2024). "Hypertension and erythropoietin were more common among our dialysis patients with hypothyroidism." (PMID 36655149, 2023). "Besides the systemic inflammation mechanism, RDW was thought to reflect oxidative stress, malnutrition, dyslipidemia, hypertension, erythrocyte fragmentation and erythropoietin alterations." (PMID 36263092, 2022). "For example, sustained erythropoietin treatment may bring side effects (e.g., hypertension and thrombosis) and increase mortality, and FGF-23 neutralization failed to mitigate LVH but increased aortic calcification and the risk of mortality in CKD rats." (PMID 35903671, 2022). "However, hypertension is a common complication of erythropoietin treatment and higher doses of erythropoietin stimulating agents always lead to a higher BP response." (PMID 36285374, 2022).
Hypertension (continued). "The increase in RDW may be related to a variety of potential metabolic abnormalities, such as inflammation, oxidative stress, telomere shortening, malnutrition, dyslipidemia, hypertension, erythrocyte fragmentation, and abnormality of erythropoietin function." (PMID 36204660, 2022). "Using a nitric oxide synthase inhibitor to recreate hypertension in a rat hypertension model, administration of oral recombinant human EPO reduced NOX-dependent O2•- production, enhanced the expression of suppressor cytokine signaling-1, and improved vasodilation." (PMID 35741081, 2022). "Also, regular blood pressure monitoring is needed in patients receiving erythropoietin therapy as both normotensive and previously hypertensive patients can develop hypertension post-therapy." (PMID 33628672, 2021). "Role of adrenomedullin in EPO-induced hypertension is uncertain." (PMID 33628672, 2021). "Also, an attempt has been made to find out the role of blood viscosity in erythropoietin-induced hypertension." (PMID 33628672, 2021). "The incidence of hypertension with erythropoietin use is estimated to be around 10% to 15%." (PMID 33628672, 2021). "We could not derive a definite conclusion regarding the role of blood viscosity in erythropoietin-induced hypertension as the literature reviewed had contradicting results." (PMID 33628672, 2021). "Thus, our results also suggest that EPO and NO protect the respiratory neural control system against physiological (such as at high altitude) and/or pathological (such as sleep apnea and hypertension) hyperactivation." (PMID 34594222, 2021). "Additionally erythropoietin exerts antinatriuretic effect, and by altering sodium excretion, it can lead to hypertension." (PMID 33628672, 2021). "However, the use of erythropoietin is limited due to the side effects such as erythrocytosis, increased thrombosis, hypertension, growth progression, and the formation of new tumors." (PMID 32942669, 2020). "However, long periods of recombinant EPO treatment can result in cardiovascular diseases including hypertension, polycythemia, stroke, and seizures, with hypertension being the most common." (PMID 32290638, 2020). "In addition, 2 patients appearing hypertension and headaches after first dose of rHu-EPO and 1 patient suffering from gastrointestinal symptoms after receiving intravenous iron were excluded." (PMID 33213494, 2020). "Our results suggest that activation of the βCR on the vascular endothelium with EPO or ESP specifically impairs endothelial vasodilatory responses to ACh, which may contribute to the pathogenesis of EPO‐induced hypertension." (PMID 29939494, 2018). "However, potential benefits need to be balanced against the risks of adverse arterial effects and the complications of EPO use, including hypertension and pure red cell aplasia." (PMID 27142617, 2016). "Focusing on advanced stages of CKD (stages 3–5, n = 130) did not change the associations of GFR, EPO and ferritin with hepcidin levels, whereas hypertension and dyslipidemia lost significance (detailed data not shown)." (PMID 25894587, 2015). "However, treatment can result in rhEPO levels greatly exceeding the normal physiological range for endogenous EPO, and there is evidence that this contributes to hypertension in patients with CKD." (PMID 25392999, 2014). "However, the side effects of erythropoietin (hypertension, risks of thrombotic events) make it unattractive in the hip fracture population and the cost of erythropoietin used in these studies is high, over £200 per patient." (PMID 24015990, 2013). "EPO can account for some use-limiting adverse effects, as it may promote hypertension, retinopathy, neurotoxicity and thrombotic events when it is used in the repetitive and large doses that are required for adequate tissue protection." (PMID 21085572, 2010).